SPP1 (secreted phosphoprotein 1)
Diseases named in the same sentence as SPP1 in open-access papers (continued):
Sharing a sentence is not in itself a finding about the gene and the disease.
tumor (continued). "The correlation observed in our study between higher levels of SPP1 and the infiltration of dendritic cells in the tumor microenvironment was significant." (PMID 38275392, 2023). "By examining intercellular communications, we found that MDSCs were able to suppress the activity of cytotoxic CD8+ T cells and recruit SPP1+ TAMs to shape an immunosuppressive microenvironment that promoted tumor angiogenesis." (PMID 37475874, 2023). "SPP1, which contributes to tumor cell evolution and TME reprogramming, has been reported to be a valuable therapeutic target for HCC." (PMID 37287752, 2023). "It is thought that SPP1 is mostly secreted by tumor cells and, accordingly, we found high levels of Spp1 in the MOSE-LTICv cells." (PMID 38264656, 2023). "the TCGA-HNSC cohort data indicated that the infiltration of SPP1+ TAMs was significantly higher in tumor samples than in the adjacent normal tissues, consistent with our scRNA-seq data." (PMID 37853464, 2023). "Despite the strong correlation between the high-SPP1 group and improved tumor immunogenicity as well as inflamed antitumor immunity, it is still necessary to further explore the potential molecular mechanism how SPP1 reacts with immune-related cells." (PMID 38111044, 2023). "These tumours had a high number of dysregulated genes, a high expression of immune suppression markers (i.e. SPP1) and the highest number of nodal involvements after surgery." (PMID 37258531, 2023). "In many previous studies, the SPP1 gene was recognized as an oncogene because its expression level is usually higher in tumor tissue than in normal tissue." (PMID 38111044, 2023). "Studies have demonstrated that an interaction between CD44 and SPP1 induces cell signaling and modulates tumor cell activation, motility, and adhesion, resulting in cancer progression and metastasis." (PMID 38235128, 2023). "Silencing of the OPN gene (Spp1) dramatically inhibited tumor growth in vivo in an orthotopic model, indicating that OPN has an important promoting role in the proliferation of MPM cells." (PMID 37398648, 2023). "We investigated the expression of senescence prognostic genes in scRNA-identified immune cell populations and identified SPP1+ macrophages as an important TME component that leads to tumor senescence." (PMID 37090726, 2023). "Strikingly, SPP1-CD44 signaling was present between hepatocytes and T/NK cells, macrophages, and fibroblasts in tumor samples, but not in normal samples adjacent to cancer, further supporting the critical role of SPP1 in the tumor ecosystem." (PMID 36860314, 2023). "Vegfa+ macrophages exhibited high expression of Spp1, Vegfa, and Mmp12, and enriched in anti-inflammatory pathways, sharing the similarity with the previously termed SPP1+ macrophages, which have an enrichment of tumor angiogenesis and protumorigenic role." (PMID 37115931, 2023). "Cell-cell communication analysis using CellChat reveals critical role for SPP1-mediated crosstalk in tumor periphery." (PMID 38127790, 2023). "Given this, we next turned to define the requirement for KCs and T cells in mediating anti-tumor programming of Spp1+MΦs." (PMID 37816712, 2023). "SPP1 influences the malignant biological activity and immune escape of tumor cells and its overexpression facilitates the progression and metastasis of LIHC." (PMID 37346073, 2023). "The SPP1/CD44 interaction has been shown to be associated with promoting cell proliferation and stemness of tumor cells." (PMID 37583898, 2023). "The expression of APOE and SPP1 has been detected in macrophages during tumor progression, with SPP1 becoming highly expressed in lipid-associated macrophages." (PMID 37762157, 2023). "The number of SPP1+ macrophages significantly increases in the tumor microenvironment, which is correlated with poor prognosis." (PMID 38347955, 2023). "Previous studies have suggested that SPP1 can regulate metastasis and invasion of the tumor as a part of the extracellular matrix‐receptor interactions." (PMID 37194413, 2023).
tumor (continued). "There was also a strong enrichment of tumor angiogenesis and tumor vasculature pathways in SPP1+ TAMs." (PMID 38347955, 2023). "In contrast, CCL18+ macrophages showed a dominant M2-like phenotype with the high expression of CD163, MARCO, and CSF1R, suggesting their stronger tumor-promoting role than SPP1+ macrophages." (PMID 35347134, 2022). "This suggests that SPP1 produced by tumor cells exerts tumor-mediated immunoregulation through NK cells and T cells." (PMID 36180422, 2022). "Among that, the protein expression of TNFRSF21, JAG1, and SPP1 were evidently up-regulated in tumor than normal tissues." (PMID 36274838, 2022). "Elevated levels of SPP1 in ccRCC are correlated with larger tumor size, advanced stage, higher Ki-67 proliferation index, and decreased overall survival." (PMID 36180422, 2022). "SPP1+ TAMs are enriched for pathways involved in tumor angiogenesis, tumor vasculature and colorectal adenoma, while C1QC+ TAMs are enriched for complement activation and antigen processing and presentation pathways." (PMID 36189323, 2022). "Here, by performing single-cell RNA sequencing on 144,878 cells from 14 pairs of iCCA tumors and non-tumor liver tissues, we find that S100P and SPP1 are two markers for iCCA perihilar large duct type (iCCAphl) and peripheral small duct type (iCCApps)." (PMID 35347134, 2022). "We also found that SPP1+ macrophages were enriched for the M2 macrophage gene sets, indicating their tumor-promoting functional phenotype in the GC TME." (PMID 36612160, 2022). "We previously demonstrated an almost ten-fold increase in the OPN (SPP1) transcriptional level in tumor tissue of HsS4D phenotype compared to LsS4D and about a fourfold increase in MMP7, which is implicated in OPN cleavage." (PMID 36338570, 2022). "Taken together, our study sheds light on the intratumor heterogeneity mediated by the expression pattern of SPP1 and the distribution of tumor-specific SPP1+ macrophages, as well as the cancer region-specific SPP1–CD44 axis." (PMID 36612160, 2022). "Many reports suggested that the levels of circulating SPP1 and/or an increased level of SPP1 expression in tumor cells are correlated with a poor prognosis in NSCLC." (PMID 36139536, 2022). "Cell migration, ECM–receptor interaction, and tumor angiogenesis pathways were enriched in SPP1+ TAMs, while the complement pathway activation and antigen processing and presentation pathways were enriched in C1QC+ TAMs." (PMID 35558087, 2022). "Single-cell RNA sequencing (scRNA-seq) showed that SPP1+ macrophages are enriched in tumor tissue, and the high expression of SPP1 contributed to the resistance to PD-L1 blocking immunotherapy." (PMID 36532065, 2022). "The pan-cancer landscape of SPP1 for diagnosis, prognosis, and tumor immune infiltration was investigated." (PMID 36292645, 2022). "Initially, we used the Oncomine database to analyze the expression level of SPP1 in different tumor and normal tissues." (PMID 35067176, 2022). "We constructed a tumor xenograft model in nude mice to evaluate the role of SPP1 in ESCA tumor progression and resistance to radiation." (PMID 35593388, 2022). "The SPP1 gene is located in 4q22.1 and encodes the secreted phosphoprotein 1, which is involved in cell adhesion to the extracellular matrix (ECM), tumor proliferation, migration, chemoresistance, and macrophage polarization." (PMID 36292645, 2022). "SPP1 promotes epithelial-mesenchymal transition during metastasis and regulates the tumor microenvironment in favor of metastasis." (PMID 35067176, 2022). "For instance, heterogeneity of APOE+ tumor-associated macrophages (TAM, c19) were exhibited by the complementary distribution of C1QC+ and SPP1+ cells, which is consistent with a previous report on pan-cancer scRNA-seq analysis." (PMID 36333338, 2022). "We found that the expression of SPP1 was significantly correlated with tumor purity of 13 cancer types (p < 0.05)." (PMID 36585688, 2022).
tumor (continued). "The expression of SPP1 and its relationship with tumor prognosis, immune invasion, tumor microenvironment, and immunotherapy were analyzed using the R language." (PMID 35067176, 2022). "SPP1 was positive for foamy-like macrophages existing in the tumor nests or glandular area, but SPP1 was less expressed on smaller-sized macrophages in the stroma." (PMID 36139536, 2022). "Secreted phosphoprotein 1 (SPP1) is involved in immune regulation, cell survival, and tumor progression." (PMID 35067176, 2022). "SPP1, also known as osteopontin, encoded by the human gene SPP1 is a cytokine upregulating expression of IFN-γ and IL-12, which is a critical mediator in tumor-associated inflammation and promotes metastasis of cancers." (PMID 36038839, 2022). "TAMs and CAFs were classified according to their tumor origin and high expression of SPP1, C1QB, IL1B, S100A8, S100A9 and type I collagens (COL1A1 and COL1A2)." (PMID 36209225, 2022). "SPP1, a key signature in the established prognostic model, plays a pivotal role in the tumor immune microenvironment and tumor progression." (PMID 36292645, 2022). "This study demonstrated that the increased expression of SPP1 worsens the prognosis of CRC patients by mediating tumor evasion from immune responses." (PMID 36091047, 2022). "The SPP1 expression was revealed as a relatively high level in tumor tissues (p < 0.05) and a positive correlation with tumor staging (p < 0.05)." (PMID 36676937, 2022). "Previous studies demonstrated that the level of circulating SPP1 and/or increased SPP1 expression on tumor cells were correlated with a poor prognosis in various cancers, including NSCLC." (PMID 36139536, 2022). "In general, our results showed the positive regulation of genes associated with processes related to tumour progression and metastatic process, including genes involved in extracellular matrix (ECM) interaction and cell adhesion, such as SPP1 and THBS2." (PMID 36077612, 2022). "It has been reported that SPP1 can bind to various integrins or certain variants of CD44 and activate downstream signaling pathways to promote tumor progression." (PMID 36612160, 2022). "SPP1 encoded osteopontin (OPN), the physiological ligand for CD44, acts as an immune checkpoint to suppress T cell activation and confers host tumor immune tolerance in human colon carcinoma that correlated with decreased patient survival." (PMID 35634447, 2022). "More importantly, in the occurrence and development of tumors, SPP1 has been reported to be critical in tumorigenesis and tumor progression in many cancer types, and the high expression of SPP1 is often correlated with poor prognosis." (PMID 35593388, 2022). "We measured the tumor volume and tumor weight in each group and the results showed that the SPP1 overexpression group had the largest tumor volume and weight while the SPP1 knockdown group had the smallest." (PMID 35593388, 2022). "scRNA-seq of tumour samples revealed that a subpopulation of TAMs presented with high expression of SPP1, the macrophage scavenger receptor MARCO, and MHC II class genes." (PMID 36154923, 2022). "Further analysis of myeloid cell subtypes revealed a dramatic increase in SPP1+ macrophages in tumor tissue." (PMID 35365629, 2022). "We investigated the expression of HRAGs in HCC tumor tissues, and their associations with survival, and constructed a novel prognostic model based on three HRAGs (ANGPT2, SERPINE1, and SPP1) to stratify HCC patients according to their estimated survival." (PMID 36110938, 2022). "The immune/stromal scores correlated positively with the SPP1 expression, and the relationship was affected by tumor heterogeneity and immunotherapy." (PMID 35067176, 2022). "Macrophage clusters from different tumor types were diverse; additionally, SPP1+, C1QC+, ISG15+, and FN1+ TAMs were primarily enriched at the tumor site." (PMID 35504878, 2022).
tumor (continued). "The transformation of fibroblasts to CAF is caused by paracrine signals from the primary tumor through, including but not limited to, TGFb1, PDGF and osteopontin (OPN, aka SPP1)." (PMID 36148042, 2022). "In recurrent cSCC, CD8+ T cells showed high exhaustion and low inflammatory features, while SPP1+ TAMs displayed global pro-tumor characteristics, including decreased phagocytosis and inflammation and increased angiogenesis." (PMID 36438481, 2022). "Patients with high SPP1+ TAMs were prone to suffer from lymph node (LN) metastasis, multiple tumors, and larger tumor size (all P < 0.050)." (PMID 35558087, 2022). "It should be noted that SPP1 is also expressed in TAMs, but the expression is much lower than tumor cells." (PMID 36476645, 2022). "By modulating epidermal growth factor (EGFR) activation, SPP1 can influence the immune escape and malignant biological activity of tumor cells, and its overexpression enhances HCC development and metastasis." (PMID 36353638, 2022). "We next used TIMER and TISIDB online database to further explore the effects of SPP1 expression on tumor infiltration immune cells." (PMID 36585688, 2022). "We standardized the relative expression (RE) of the target gene SPP1 in tumor tissue and normal tissue by combining a single reference gene and two combined genes." (PMID 36467891, 2022). "We confirmed that the seven S100P- iCCAs showed high expression of SPP1 both at the cellular (87.17% of S100P- iCCAs’ tumor cells) and tissue level." (PMID 35347134, 2022). "The presence of OPN in CA IX positive tissues is in line with investigations of tumor tissues which showed a positive correlation between CA9 and SPP1 mRNA expression in different types of cancer." (PMID 35055064, 2022). "We identify a fingerprint consisting of LGALS9-SLC1A5, SPP1-PTGER4 as tumor and macrophage-derived ligand–receptor interaction pairs, linked to tumor aggressiveness." (PMID 36476645, 2022). "Increased expression of SPP1 was only positively correlated with certain tumor stages, such as COAD, ESCA, LIHC, and READ." (PMID 35067176, 2022). "Single-cell analysis also suggests that EMT is the biological process in tumor cells most relevant to SPP1+TAMs." (PMID 36117852, 2022). "In order to further understand the exact mechanism of SPP1 promoting tumor development, this study conducted in-depth bioinformatics analysis on the cancer-promoting mechanism of SPP1." (PMID 35154316, 2022). "Several ligands were specifically upregulated in the tumor cell population when compared to adjacent kidney, including SPP1 and CD70." (PMID 36180422, 2022). "Exogenous or tumor-secreted SPP1 has been shown to directly act on endothelial cells to promote angiogenesis via AKT activation." (PMID 36230774, 2022). "From the results of transcriptome sequencing and other research, SPP1 is a secreted protein that promotes tumor proliferation and is higher in tumor tissue than in normal tissue." (PMID 36467891, 2022). "The functions of SPP1 include bone metabolism, immune regulation, wound healing, cell survival and tumor progression." (PMID 35154316, 2022). "To better understand the expression and biological function of SPP1 in GC, we revealed the presence of a complex tumor ecosystem in GC, in which SPP1+ macrophages were enriched in cancerous tissues and cancer cell-containing regions." (PMID 36612160, 2022). "SPP1 overexpression was positively correlated with the severity of tumor malignancy and chemoresistance in multiple cancer types." (PMID 36003400, 2022). "Previous studies have illustrated that tumor-driven hypoxia promotes the expression of SPP1, which in turn promotes tumor angiogenesis and immunosuppressive microenvironment." (PMID 36110938, 2022). "In ESCC, down-regulated expression of SPP1 can repress cell motility, cell invasion in vitro and tumor formation, lymph node metastasis in nude mice." (PMID 36038839, 2022).
tumor (continued). "SPP1 was related to the abundance of tumor-infiltrating Tregs and macrophages in many tumor tissues." (PMID 36292645, 2022). "SPP1 is also expressed in tumor cells, and many studies demonstrated that a high level of circulating SPP1 is correlated with a poor prognosis in various cancers." (PMID 36139536, 2022). "For example, SPP1+TAMs, which are different from the classic classification of TAMs and accounts for a large proportion of macrophages within the tumor, have a tumor-promoting phenotype under hypoxic conditions." (PMID 35281061, 2022). "To further assess the spatial organization of FAP+ fibroblasts and SPP1+ macrophages, we performed spatial transcriptomics (ST) with tumor tissue sections from four CRC patients." (PMID 35365629, 2022). "We also confirmed that SPP1 expression is elevated in tumor cells but its expression is heterogeneous, which is consistent with previous publications." (PMID 36476645, 2022). "More recently, it has been confirmed that aberrant expression of SPP1 was found in various malignancies, and it was closely related to the tumor biology, such as proliferation, migration and invasion." (PMID 36266702, 2022). "Subsequently, we analyzed DEGs between tumor and normal tissues and selected the top five DEGs with the highest expression, which were SPP1, AKR1C2, AKR1B10, AGT, and EPHX1 in tumor tissues and NKG7, KLRD1, KLRB1, CCL5, and CST7 in normal tissues." (PMID 35967424, 2022). "Our goal was to reveal the prognostic value of SPP1 in GC and its role in the GC tumor microenvironment based on multi-transcriptomic analysis." (PMID 36612160, 2022). "Given the novel phenomenon that the human ESCA cells increased SPP1 expression after radiation, we propose that SPP1 significantly contributes to the tumor relapse and the development of therapeutic resistance to radiotherapy in human ESCA." (PMID 35593388, 2022). "To investigate the role of SPP1 in tumor immunotherapy, we downloaded and analyzed immunotherapy datasets from the GEO database including GSE111636, GSE67501, GSE26383, GSE79691, and GSE100797." (PMID 35067176, 2022). "We also found that despite S100P + SPP1− iCCAphl often had smaller tumor size, it had more lymph node metastases, and higher levels of CA19-9, Ki67, and CEA compared with S100P-SPP1 + iCCApps." (PMID 35347134, 2022). "Real‐time PCR analysis of SPP1 in tumours showed that SPP1 expression was significantly decreased in the combination‐therapy group compared to either single‐treatment groups." (PMID 35184394, 2022). "Immunohistochemistry microarray was used to further confirm that protein expression of CD24, MMP1, SDC1, and SPP1 was much higher in tumor sections than in Para cancerous tissues." (PMID 35037689, 2022). "We found that SLC1A5 and SPP1 are mainly produced by tumor cells while LGALS9 and PTGER4 are mainly expressed in TAMs." (PMID 36476645, 2022). "SPP1 can promote tumor invasion and inhibit the antitumor ability of immune cells through activating downstream signaling pathways." (PMID 36003400, 2022). "The SPP1+ macrophages were similar to the tumor-associated macrophage (TAM) population in the immune microenvironment, which aids tumor cell immune escape and promotes tumor angiogenesis." (PMID 36569953, 2022). "For example, specific subgroup of macrophages, such as C1Q (+) and SPP1 (+) TAMs can regulate tumor immune microenvironment via interaction with T cells and CAFs respectively, which were identified in NMF clustering of TAMs." (PMID 35784460, 2022). "This study provided the basis for a deeper understanding of the potential mechanism of SPP1 tumor immunity and its related cancer biomarkers." (PMID 35067176, 2022).